IL1B (interleukin 1 beta)
Diseases named in the same sentence as IL1B in open-access papers (continued):
Sharing a sentence is not in itself a finding about the gene and the disease.
infection (continued). "Additionally, Ifnb1 transcript was again induced during cytosolic infection, where Il1b expression was induced during PAM-treatment alone, as well as during infection with wild-type or Δhly L. monocytogenes." (PMID 34555127, 2021). "Processing of IL-1β and IL-18 could also be inflammasome-independent during infections due to host intrinsic proteases, and this has been extensively reviewed elsewhere." (PMID 33735255, 2021). "Both young and old RMs showed increased infiltration of inflammatory immune cells (CD8+, CD163+, and CD11b+ cells) after infection, whereas inflammatory factor-secreting cells (IFN-α+, IL-6+, and IL-1β+ cells) were only significantly induced in old RMs following infection." (PMID 34471088, 2021). "IL-1β activates the synthesis of nitrous oxide, prostaglandin E2, and platelet-activating factor, which expedite the vascular changes responsible for inflammation and increase blood flow to the injury or infection site." (PMID 34299815, 2021). "In addition, IL-1β production in murine dendritic cells and macrophages after infection with encephalomyocarditis virus (EMCV) or vesicular stomatitis virus (VSV) is dependent on NLRP3 inflammasome." (PMID 34201847, 2021). "By stimulating macrophages with cell-free supernatants, representing a high or low abundance of PE/PPE proteins, we could show differential regulation of IL-1B similar to infection with live M. tuberculosis CDC1551 and Δppe38-71 strains." (PMID 34276695, 2021). "Moreover, 24 h after infection, we detected the overexpression of IL-1β (precursor) and IL-1β (mature) proteins in cells treated with live bacteria at MOI 50 upwards and TNF-α protein overexpression exhibited at MOI 1 and above." (PMID 34831265, 2021). "The IL-1β was upregulated in all infection groups on day 3 with similar levels." (PMID 34960604, 2021). "However, in the Shigella and Pseudomonas aeruginosa studies, IL-1β rose linearly along with increasing infection doses." (PMID 34869071, 2021). "Thus, we conclude that secretion of IL-1β in response to GEVs infection in vitro is mediated by NLRP3 inflammasome and NLRP3 inflammasome plays vital roles in regulating inflammatory response." (PMID 33798196, 2021). "The analysis of variance between IL-1β, IL-18, IL-6, IL-8 and caspase-1 levels, showed statistically significant differences related to the infection conditions or the time after infection (6, 18 and 24 h.p.i.)as well as the interaction between these two factors." (PMID 34947890, 2021). "Interestingly, dog cells showed clear processing of pro-IL-1β accompanied by the release of large amounts of IL-1β at 24 h post-infection." (PMID 34433041, 2021). "sCD26 concentrations in infection-triggered ME/CFS were found to be associated with activated T cells, liver enzymes, creatin kinase (CK) and lactate dehydrogenase (LDH) and inversely with Interleukin-1 beta (IL-1b)." (PMID 33889154, 2021). "Furthermore, we showed that the infection stimulated the release of inflammatory cytokines IL-1β and IL-18, induce inflammation, and eventually promoted pyroptosis of macrophages." (PMID 33678162, 2021). "Collectively, these results suggest that SARS-CoV-2 can trigger macrophages and DCs to secrete IL-6 and IL-1β, which might directly decimate lymphocytes following infection in vivo." (PMID 33995382, 2021). "IL-6, IL-12, IL-8, interferon-gamma, and IL-1β all show increased secretion 48 hours after infection; however, the greatest (and most statistically significant) increase is shown by IL-6 equating to a fourfold increase above that of the uninfected control 48 hours postinfection." (PMID 34152044, 2021). "In contrast to IL-1β, there are relatively few studies on IL-1α in infection or inflammation." (PMID 34010648, 2021).
infection (continued). "Although all species triggered type I interferon responses, the differences in the levels of IFN-β and bioavailability of IL-1β between infection conditions further strengthen the evidence of variations among rickettsiae in their ability to manipulate the host." (PMID 34935429, 2021). "The qPCR data showed that V. alginolyticus could induce the upregulation of IL-1β mRNA transcription at different infection doses (***p < 0.001) and the levels showed a trend of increasing and then decreasing." (PMID 34869071, 2021). "We found that many cytokines messenger RNAs (mRNAs), including Il1b, Il5, Il6, Il10, Il12a/Il12p70, Ifng, Ccl4, Ccl5, Tnfa, Gcsf, Cxcl1, Il1a, and Il3, were significantly induced upon B.1.351 infection in the lungs of hACE2 transgenic, BALB/c, and C57BL/6 mice." (PMID 34907154, 2021). "Moreover, IL-1β and IL-18 as pro-inflammatory cytokines prevent the infection of pathogens effectively, yet excess pro-inflammatory cytokines is harmful to the host." (PMID 34777393, 2021). "IL-1β is of great importance for host resistance against infections with Mtb." (PMID 34324582, 2021). "Surprisingly, we also observed that several genes related to inflammatory process (il1b, il10, tgfb) were repressed after 35 h of infection with the low dose of Gas1, and could be explained by a modified dynamic of gene expression over time." (PMID 34295335, 2021). "Platelet activation induces the acute phase response to infection and produces IL-1β in mice." (PMID 33618723, 2021). "We therefore examined if in murine infection with the Δmag1 strain, neutralization of IL-1β by antiserum during the acute phase of mouse infection could restore parasite virulence." (PMID 34006649, 2021). "The influenza virus A/FM/1/47 (H1N1) infection could substantially upregulate the serum levels of IL-1β and IL-6." (PMID 34497658, 2021). "In addition, we found that inhibition of p38, ERK, NF-κB, serine proteases and Cathepsin B resulted in significantly lower expression of pro-IL-1β compared to DMSO treated cells after CFT073 infection at MOI 1 for 4h." (PMID 34944029, 2021). "A large number of viruses have been reported to induce the production of IL-1β during infection." (PMID 34310655, 2021). "The level of hallmark innate cytokine IL-1β was not significantly influenced during the course of infection." (PMID 34777338, 2021). "As pro-IL-1B was the most differentially regulated protein, we probed for expression of this protein by Western blot 18 hours after stimulation and found similar differential regulation as observed in our infection proteomics data." (PMID 34276695, 2021). "Infection with CT can cause direct damage to sperm, reducing the sperm concentration, motility, and vitality, and can increase pH, lipid peroxidation (LPO), and even proinflammatory cytokines such as IL-1β and IL-6 in semen of infertile men." (PMID 34577786, 2021). "In addition, after challenge infection, we observed a reduction of IL-1β expression, and modulation of TNFα, TGFβ and IL10 expression." (PMID 33499363, 2021). "It has therefore been hypothesised that S. pyogenes-mediated proteolysis of IL-1β and IL-36γ during infection may trigger inflammation and lead to the development of inflammatory disease." (PMID 35003136, 2021). "ELISA quantification of IL-1β, IL-6, and IL-8 in plasma was undetectable in JM-3, A, and JC, as well as in the healthy controls, but they were detected during the acute symptomatic infection in JM (JM-1)." (PMID 34669281, 2021). "In contrast to our findings here demonstrating IL‐1β exacerbates IAV disease, studies in gene‐deficient mice have shown that IL‐18 plays a protective role during HKx31 and PR8 infection by limiting viral replication, mediating interferon‐γ production as well as NK and T‐cell responses." (PMID 33834544, 2021).
infection (continued). "Interestingly, UPR was induced in a 2 waves manner during a 24 h period, suggesting that it can influence, per se, the production of type I IFNs, guanylate binding proteins (GBPs), IL-1β, and IL-6 in latter moments during infection." (PMID 35011636, 2021). "This suggests that a change in IL-1β production may occur during infection dependent on the crosslinking of PG, with reduced PG crosslinking resulting in greater colonisation in the liver." (PMID 33788901, 2021). "Regarding the inflammatory cytokine contents in mice after infection, the contents of TNFα, IFNγ, IL-1β, and IL-18 in serum, spleen, and ileum of mice challenged with ΔhtpG strains were significantly decreased (p < 0.05) as compared with mice challenged with WT strains." (PMID 34869065, 2021). "We found that Rufomycin 4–7 effectively decreased the generation of pro-inflammatory cytokines Il1b and Il6 in macrophages as well as the intracellular survival of type strain and two clinical isolates of Mabs-R during infection." (PMID 34447358, 2021). "The pronounced increase in IL-1β production in patients with CGP is probably caused by massive stimulation of cells of monocyte–macrophage system by antigens of pathogenic flora and indicates the development of purulent infection." (PMID 33803774, 2021). "The pro-inflammatory cytokines, e.g., IL-6, TNF-α, and IL-1β, involved in the pathological processes of rejection and infection in baboon xenograft recipients, and may be associated with coagulation dysfunction." (PMID 34956220, 2021). "In vivo knockdown of intestinal il1b eliminated the anti-infection effect." (PMID 34899717, 2021). "After 12 h, the relative expression of TNFα, iNOS, IL-1β, and IL-18 in the ΔhtpG infection group was significantly lower than that in the WT infection group (p < 0.01), and the relative expression of IL-1β and IL-18 was extremely lower than that in the CΔhtpG infection group (p < 0.01)." (PMID 34869065, 2021). "In addition, we also found that inhibiting JNK increased the release of IL-1β after CFT073 infection." (PMID 34944029, 2021). "It was also shown that the production of KC, IL-10, IL-6, TNF-α, and IL-1β was significantly enhanced when bacterial loads were also significantly increased after S. pneumoniae infection at 7 days after H9N2 virus (A/Duck/Hong Kong/702/1979) infection." (PMID 33722928, 2021). "In addition, the secretion of IL-1β subsequently recruits immune cells, such as neutrophils and NK cells, to the site of infection, which also contributes to the elimination of invading viruses." (PMID 34769275, 2021). "However, post infection, levels of IL-1β and IL-6 were significantly elevated in Coch+/+ mice compared to Coch−/− mice, suggesting that cochlin is necessary for local upregulation and increased secretion." (PMID 34768980, 2021). "THP-1 macrophages were exposed to equal amounts of viable Y. enterocolitica, ΔyopBY. enterocolitica, or heat-treated Y. enterocolitica (multiplicity of infection [MOI] of 50) for 2 h, followed by quantification of a PGE2 and IL-1β by enzyme-linked immunosorbent assay (ELISA)." (PMID 34319170, 2021). "At 2 h postinfection, IL-1β and IL-18 production was reduced in both parental and NLRC4 KO THP-1 cells infected with the flagellin- or T3SS/flagellin-deficient strain in comparison with infection with wild-type S. Typhimurium." (PMID 33380493, 2021). "IL-1β and IL-8 expressions from the ileum of SI chickens were negatively correlated to the H/L ratio on day seven and positively correlated to the H/L ratio on day 21 post-infection." (PMID 34944274, 2021). "We speculate that upon infection of hMDM with T3SS/flagellin-deficient S. Typhimurium, IL-1β and IL-18 are processed in a caspase-8–dependent manner and released in a GSDMD-independent way." (PMID 33380493, 2021). "NLRP3-/- mice expressed higher levels of IL-1β than WT at day 3 post-infection." (PMID 33524073, 2021).
infection (continued). "On the opposite, LPS-primed U937 expressing NLRP3 S806A, D, or E mutants secreted IL-1β as WT U937 in response to infection by Salmonella enterica serovar Typhimurium (SL1344 strain) and transfection with poly(dA:dT), activating the NLRC4 and AIM2 inflammasomes respectively." (PMID 34615873, 2021). "Another study found that IL-1β knockout mice were protected from developing UPEC mediated UTI, which indicates that IL-1β may drive the infection." (PMID 34944029, 2021). "Similarly, infection with herpes simplex virus 1 (HSV-1), a DNA virus of the Herpesviridae family, caused strong caspase-1 activation and pro-IL-1β maturation." (PMID 34201847, 2021). "Additionally, we demonstrated elevated mRNA levels of IL1β and TNFα at the later stage of infection (28dpi)." (PMID 34899715, 2021). "Furthermore, knocking out GRA15 (an inducer of IL-1β release) in Δmag1 parasites completely inhibited all IL-1β release by host cells following infection." (PMID 34006649, 2021). "IL-1β, the second key product of inflammasome activation, was not increased post-infection, nor was there an effect on infection susceptibility in IL-1β knockout mice." (PMID 34113580, 2021). "Also, ΔCD2v/ΔMGF360-505R-ASFV infection upregulates the expression levels of phospho-NF-κB p65 and p-IκB proteins and IL-1β production are significantly lower than the GZ201801-ASFV infection." (PMID 34835302, 2021). "In response to IL-1α, IL-1β, and IL-36 stimulation, keratinocytes express and release a host of antimicrobial peptides including human beta defensins, LL-37, and S100 proteins which directly combat infection." (PMID 35003136, 2021). "Is the initial IL-1β release from the bladder epithelial cells enough to fight of the infection?" (PMID 34944029, 2021). "In fact, IL-1β levels may either spike before clinical presentation or represent only a local phenomenon throughout the infection, or may be marginally involved in the immune response against HAdV." (PMID 34578465, 2021). "However, our observations here indicate that infection with IAV which lacks NS1 led to the loss of NLRP3 inflammasome activation and IL-1β release, while enhancing the assembly of SGs and induction of IFN-β." (PMID 33766561, 2021). "An in vitro study proved that the Z. morio hemolymph can reduce the expression of pro-inflammatory factors, including interleukin-1β (IL-1β) and interleukin-18 (IL-18), which suggests that Z. morio hemolymph can be used as a novel therapeutic drug to reduce pathogen infection in animals." (PMID 34941846, 2021). "However, our data demonstrated that, at later stages of infection, IL-1β was indeed downregulated by C. jejuni, whereas supplementation of L. fermentum increased its abundance significantly at 7 dpi." (PMID 33477806, 2021). "Importantly, although similar developmental transition forms were common to both chlamydial strains, only infection with CtD resulted in neutrophil cytotoxicity and IL-1β secretion that was dependent on chlamydial mRNA synthesis." (PMID 34526512, 2021). "Importantly, M. canis also triggered IL-1β production in vivo, after intraperitoneal infection of WT mice, but IL-1β release was completely abolished in NLRP3- or ASC-deficient mice." (PMID 33343578, 2020). "A more focused investigation of infection-specific markers IL-1α, IL-1β, IL-6, IL-8, MCP-1, MIP-1α, and MIP-1β could provide insight into the power of these cytokines to discriminate aseptic vs. septic tissues." (PMID 32867801, 2020). "In particular, infection of EC by P. gingivalis markedly increased the levels of pro-inflammatory molecules including interleukins (IL-1β, IL-8), Regulated on Activation Normal T Cell Expressed and Secreted (RANTES) and interferon gamma receptor protein-10 (IP-10)." (PMID 32901057, 2020).
infection (continued). "Inflammasomes are protein scaffolds required for the activation of caspase-1 and the subsequent release of interleukin (IL)-1β, IL-18, and danger signals, as well as the induction of pyroptotic cell death to restore homeostasis following infection and sterile tissue damage." (PMID 32962268, 2020). "MAYV infection induced acute production of several pro-inflammatory molecules in the spleen such as IL1-β and IL-6 from days 1 to 7 of infection; IFN-γ from days 1 to 5 and finally, TNF-α at the early time-points of 1 and 3 days post-MAYV inoculation." (PMID 32210270, 2020). "Further, infection with an SH-deficient mutant RSV failed to produce IL-1β from lung epithelial cells, indicating that SH is responsible for inflammasome activation and IL-1β production during RSV infection." (PMID 31952261, 2020). "In addition, proinflammatory cytokines such as TNF-α, IL-1β, IL-6, and IL-8 trigger and rapidly amplify the inflammatory response to limit the spreading of the infection." (PMID 32373312, 2020). "As above, H. pylori infection of THP1 monocytes secreted significantly less mature IL-1β, thus we hypothesized that signal-2 for activation is missing upon infection." (PMID 32230726, 2020). "IL-1β is required for the early containment of infection via priming of T cell activation." (PMID 32521796, 2020). "An experimental study in a murine model infected with L. amazonensis, L. braziliensis, and L. infantum chagasi showed that IL-1β production derived from the activation of the NLRP3 inflammasome led to host resistance to infection by the production of nitric oxide (NO)." (PMID 33192178, 2020). "IL-1β and its related family member IL-1α (also significantly up-regulated in PRRSV-infected PAMs) are both potent pro-inflammatory cytokines, which are produced by activated macrophages in response to pathogenic infections." (PMID 33198300, 2020). "Il1β, Tnf, Il6, Ccl2, Ccl5, and Cxcl10 mRNAs were all increased in the CNS after infection." (PMID 32047134, 2020). "Moreover, secondary drastic increase of the levels of TNF-α, IL-1β, IL-6, and IL-8, as well as elevated IL-10, was observed at the terminal phase of infection." (PMID 33553280, 2020). "Where full-length inactive IL-1β (31 kDa) was induced by K181 infection over mock, ∆M36 infection exhibited increased cytosolic levels of both full-length and processed (activated) IL-1 β (17 kDa), suggesting that ∆M36-induced apoptosis is accompanied by enhanced inflammation." (PMID 33126536, 2020). "Such TNF-α and IL-1β overexpression lasted for at least 8 h post-infection." (PMID 32117805, 2020). "In addition to non-expression of the inflammasome pathway signaling, L. infantum was also unable to activate caspase-1 and IL-1β production in early and later periods post-infection." (PMID 31961876, 2020). "Infection of macrophages induces a shift from oxidative phosphorylation to glycolysis which promotes phagocytosis and enhances production of protective pro-inflammatory cytokines such as IL-1β." (PMID 32425944, 2020). "Interestingly, after SVCV infection, il1b was significantly overexpressed only in the WT and ptena−/− larvae, but it remained unaltered in the ptenb−/− larvae, which was the zebrafish line with the highest constitutive expression of this cytokine." (PMID 32357549, 2020). "In addition, the NLRP3/caspase-1/IL-1β pathway plays an important role in leukocyte aggregation and fighting infection during Aspergillus fumigatus infection." (PMID 32148650, 2020). "Following the infection of the periodontal pathogen, namely P. gingivalis, it was found that the release of IL-1β, IL-6, and IL-18; the gene expression of pro-IL-1β and pro-IL-18; and the activity of caspase-1 in wild-type mice were significantly enhanced in comparison to NLRP3-deficient mice." (PMID 33271934, 2020). "In our experimental infection tool, we found high levels of ROS and IL-1β production." (PMID 33322794, 2020).